EGFR (epidermal growth factor receptor)
Diseases named in the same sentence as EGFR in open-access papers (continued):
Sharing a sentence is not in itself a finding about the gene and the disease.
cancer (continued). "Luo suggested that patients with pulmonary adenocarcinoma who had scar cancer or had old TB lesions had a higher probability of having EGFR mutations, especially exon 19 deletions." (PMID 23647947, 2013). "Of the Cancer Census genes, we first identified an EGFR mutation (c.2224G>A, p.V742I) in a diffuse-type EGC with MSI-high." (PMID 24376576, 2013). "It has to be noted that besides HER2-imaging agents, there are currently several new Affibody molecules targeting other cancer-associated receptors, e.g. EGFR, IGF-1R, PDGF-Rβ and HER3, under development." (PMID 23936372, 2013). "Dysregulation of EGFR expression is associated with several key features of cancer, such as autonomous cell growth, apoptosis inhibition, invasion, and metastasis." (PMID 23710458, 2013). "Molecular genetic properties of individual cancers such as epidermal growth factor receptor (EGFR) mutations impact the likelihood of achieving clinical benefit with treatment." (PMID 24100924, 2013). "H1975 cancer cell line with mutations in EGFR exons 21 (L858R) and 20 (T790M) was refractory to reversible EGFR-TKIs, gefitinib, and erlotinib, but was sensitive to irreversible EGFR-TKIs, such as BIBW2992 (afatinib)." (PMID 23533466, 2013). "These truncated soluble EGFR variants have been detected in several cancer types, and their levels, circulating as well as in tumor tissues, have been used as prognostic and predictive markers for ovarian, cervical, lung, and breast cancers." (PMID 24078813, 2013). "Many reports suggest that EGF and EGFR are critical in cancer progression and their gene polymorphisms are correlated with susceptibility to GC." (PMID 24454509, 2013). "The reference sequence was a 225 bp segment of the EGFR gene which is known to harbor cancer related mutations." (PMID 23349847, 2013). "The enhanced EGFR signaling observed in EGFR-mutated cancer cells mediates the hallmarks of cancer in different cell types through the activation of pro-survival signaling pathways, including PI3K/Akt, MAPK and JNK." (PMID 23434665, 2013). "Acquired resistance has been associated with a secondary mutation in the EGFR gene, T790M, which has been detected in approximately 50% of cancers with acquired resistance to EGFR-TKIs." (PMID 24339922, 2013). "EGFR antagonists like erlotinib and gefitinib are recommended in the low percentage of cancers with EGFR-tyrosine kinase mutations." (PMID 23711430, 2013). "We recently found that (−)-epigallocatechin-3-gallate as well as heat shock protein 90 inhibitors cause down-regulation of the EGFR via phosphorylation at Ser1046/1047 through p38 MAPK in human cancer cells." (PMID 22788833, 2012). "Whereas Ras mutations occur in ~30 percent of human cancers, activation of Ras signalling pathways (e.g. via epidermal growth factor receptor [EGFR] amplifications) is a nearly ubiquitous characteristic of human cancers." (PMID 22917272, 2012). "Cortactin is thought to promote cancer cell proliferation by activating Akt, suggesting that factors related to resistance to EGFR TKIs are associated with the PI3K/Akt pathway." (PMID 22545054, 2012). "Radiation can increase the expression of EGFR, which has been implicated in increasing the radiation resistance of cancer cells." (PMID 22229096, 2012). "In practice, therapy that targets EGFR gene mutations in primary tumors has extended the theme of targeted cancer therapies." (PMID 22991510, 2012). "For example, EGFR (epidermal growth factor receptor) is an oncogene within 7p11.2 whose mutations or amplifications have been shown to contribute to uncontrolled cell division (a predisposition for cancer)." (PMID 22839576, 2012). "Existing Reactome pathways are updated on a regular basis, and additional cancer variants and anti-cancer drugs implicated in EGFR, FGFR and PI3K/AKT pathways will be included as information on their function becomes available." (PMID 24213504, 2012).
cancer (continued). "To date, we have limited information about the interference of the specific cancer mutations of EGFR and PIK3CA with metabolic responses of cells exposed to glucose deprivation." (PMID 22662165, 2012). "Aberrant coexpression and collaboration of EGFR and ErbB2 is widespread in cancers and has been associated with poor prognosis." (PMID 22481932, 2012). "Bronchioid is represented by patients who are female and nonsmoking, who have a superior survival outcome, and who present with well-differentiated, bronchioloalveolar morphology, early stage and EGFR mutated cancers." (PMID 22590557, 2012). "In cancer patients who have mutations in the TK domain of EGFR, very little growth factor is needed to flip on the switch, and once turned on, the cancer cell is driven to grow and proliferate through this 1 signal." (PMID 26316937, 2012). "EGFR alterations in cancer can be divided mostly in two categories: mutations in exons 18-21, which encode the tyrosine kinase portion of the receptor, and gene and protein overexpression." (PMID 23207070, 2012). "After lengthy exposure to inhibitors, cancer cells switched dependence between EGFR and HER2, but in both cases, HER3 was the common association partner." (PMID 23198146, 2012). "Up-regulation and/or over-expression of EGFR signaling have been associated with cancer-related processes, including uncontrolled cellular proliferation and autocrine stimulation of tumors producing their own growth factors." (PMID 22253908, 2012). "In cancer, it is possible that mutations would cause EGFR to remain constitutively active even in differentiated cells, resulting in maintenance or acquisition of self-renewal properties." (PMID 22384257, 2012). "Despite encouraging developments, EGFR-directed therapies are effective only in a relatively small percentage of cancer patients underlining the need for additional combination treatment options." (PMID 22289787, 2012). "Viruses often associated with cancers, such as the hepatitis B virus, which is associated with hepatocellular carcinoma, lead to upregulation of EGFR signaling." (PMID 22754566, 2012). "Enhanced activation of the IGF1R has been recognized as a major cause of resistance against EGFR-targeted therapies in cancer cells of different origin." (PMID 22815959, 2012). "Nuclear EGFR has been associated with poor clinical prognosis in diverse cancer types, including breast cancer, ovarian cancer, and oropharyngeal and esophageal squamous cell carcinomas." (PMID 22520625, 2012). "The pathways downstream of the epidermal growth factor receptor (EGFR) have often been implicated to play crucial roles in the development and progression of various cancer types." (PMID 22548923, 2012). "Signaling through EGFR has been implicated in various processes that contribute to cancer initiation and progression, including cell proliferation, drug resistance, tumorigenicity, invasion, and metastasis." (PMID 22384257, 2012). "Activating mutations in the EGFR/Ras/MAPK pathway are commonly found in human cancers and mutations in several components of the Ras/MAPK pathway have been shown to cause Noonan syndrome as well as several related developmental disorders." (PMID 22558469, 2012). "These mutants grow selectively in cancer cells with high levels of cellular thymidine kinase (TK), and constitutively activated EGFR/Ras pathway signalling complements the loss of the viral gene products." (PMID 22216938, 2012). "Although EGFR overexpression is associated with radioresistance in cancer, EGFR mutations in NSCLC have been shown to confer radiosensitivity in vitro." (PMID 23110940, 2012). "Gefitinib and erlotinib, small tyrosine kinase inhibitors, are approved for the clinical treatment of cancers harboring specific EGFR mutations." (PMID 24213504, 2012). "In spite of excluding the patients with a KRAS mutation in their cancer from receiving anti-EGFR therapy, the response rates in the patients with WT KRAS are of the order of 17%–60%." (PMID 23097702, 2012).
cancer (continued). "Mitogen inducible gene 6 (MIG-6), mainly known as a negative feedback inhibitor of the epidermal growth factor receptor (EGFR) family, is a tumor suppressor gene that is associated with many human cancers." (PMID 22701735, 2012). "Dysregulation of signaling pathways activated by EGFR occurs in nearly all forms of cancer and mutations of EGFR and molecules activated downstream of EGFR are found in cancer cells at high frequency." (PMID 22607382, 2012). "mTOR has been implicated in the resistance of various cancers to EGFR inhibitors and mTOR pathway activation is a poor prognosticator of EOC." (PMID 22481932, 2012). "The Multinational Association of Supportive Care in Cancer (MASCC) Skin Toxicity Study Group has proposed a more comprehensive grading scale specific to the dermatologic adverse events associated with EGFR inhibitors." (PMID 25031940, 2012). "The aim of this study was to investigate the existence of EGFR mutations in carcinoma of esophagogastric junction, and also to explore the possibility of treating carcinoma of esophagogastric junction using gefitinib." (PMID 22252115, 2012). "Epidermal growth factor receptor (EGFR) and its downstream factors KRAS and BRAF are mutated in several types of cancer, affecting the clinical response to EGFR inhibitors." (PMID 21943394, 2011). "A total of 120 routine diagnostic FFPE samples from patients with colorectal (n = 81), lung (n = 27) and other (n = 12) cancers were screened for mutations in the EGFR pathway." (PMID 21943394, 2011). "The epidermal growth factor receptor (EGFR) signal transduction system and its associated cell-surface receptors is one of the most studied tyrosine kinase signalling networks in cancer." (PMID 21792199, 2011). "The purpose of our study was to analyse the role of cancer-associated stroma in PDAC progression while delineating the effects of targeted ErbB3 inhibition in combination with anti-EGFR therapy." (PMID 21792199, 2011). "Atypical activity and over-expression of EGFR is associated with a number of tumors, making it a common target for cancer research." (PMID 21931838, 2011). "Data from head and neck (H&N) cancer biopsies suggested that high EGFR gene copy number (Fish+) was associated with a significantly poorer outcome (review in expert opinion:)." (PMID 22091418, 2011). "SPHK1 expression significantly correlated with the expression of many EGFR pathway genes associated with invasion of cancer cells." (PMID 21936950, 2011). "EGFR signaling is generally associated with cancer invasion, metastasis, chemotherapy resistance, and poor prognosis." (PMID 21943352, 2011). "EGFR is overexpressed in human cancer cells and is linked to metastasis and resistance to treatment." (PMID 21776270, 2011). "In several studies, cancer cell lines with high E-cadherin expression levels were found to be more susceptible to cetuximab or other anti-EGFR agents than cell lines with low E-cadherin levels." (PMID 22152101, 2011). "Signaling mediated by the Epidermal Growth Factor Receptor (EGFR) is crucial in normal development, and aberrant EGFR signaling has been implicated in a wide variety of cancers." (PMID 21264347, 2011). "The receptor directly connected to the majority of these TFs was EGFR, a tyrosine kinase coupled receptor known to be tightly associated with several cancers when overexpressed." (PMID 21880155, 2011). "This highlights the possibility of cancer cells resisting targeted treatment to molecules such as HER2 or EGFR by acquiring oncogenic mutations in downstream pathways." (PMID 22567347, 2011).
cancer (continued). "These approaches have been systematically employed to elucidate organizing molecular principles of allosteric signaling in the ABL and EGFR multi-domain regulatory complexes and analyze allosteric signatures of the gate-keeper cancer mutations." (PMID 21998569, 2011). "For EGFR TKI treated cancer recurrence patients, those with positive mutation-specific antibody IHC staining had better EGFR TKI response (p = 0.008) and longer progression-free survival (p = 0.012) than those without." (PMID 21858063, 2011). "Mitogen-activated protein kinases (MAPK) are down-stream target of EGFR signaling, and have been implicated in cancer cell metastasis." (PMID 22188922, 2011). "VHL loss also causes abnormal activation of EGFR, a receptor tyrosine kinase whose uncurbed activity is oncogenic in many types of cancers." (PMID 21949687, 2011). "EGFR amplification in cancer has been implicated in stabilizing glucose transporters, independent of its ability to increase activation of down stream signaling pathways." (PMID 21490960, 2011). "The epidermal growth factor receptor (EGFR), a member of the structurally related erbB family of tyrosine kinase receptors, has been implicated in cancer development and progression in a large number of tumors including HNSCC." (PMID 21896192, 2011). "Mutations of the ErbB kinases, and particularly EGFR, have been revealed in mutational screens of multiple cancers." (PMID 21701703, 2011). "Here, we show that acquired resistance of wtEGFR-expressing cancer cells to an EGFR TKI, gefitinib, is associated with elevated expression of breast cancer resistance protein (BCRP/ABCG2), which in turn leads to gefitinib efflux from cells." (PMID 21731744, 2011). "Constitutively active EGF-EGFR signaling due to overexpression of mutated or wild-type EGFR is found in a broad range of human carcinomas, leading to the activation of anti-apoptotic pathways and uncontrolled cell proliferation." (PMID 22022498, 2011). "In human carcinomas, excessive EGFR signalling is associated with a more aggressive phenotype and decreased patient survival, and interference with EGFR activation is the basis for a number of therapies." (PMID 21386996, 2011). "PCI has been used to deliver an IT consisting of the anti-EGFR mAb cetuximab linked to SAP into various types of EGFR+ carcinoma cell lines (colorectal, prostate, epidermoid)." (PMID 22069735, 2011). "Considering that there are (to date) no effective biomarkers in H and N cancer, additional studies are welcome in order to identify and further clarify if any underlying mechanisms of response or resistance to anti-EGFR agents exist in H and N cancer." (PMID 21274259, 2010). "Epidermal growth factor receptor (EGFR) is overexpressed in 70% of cancers and is associated with chemoresistance, poor prognosis, and advanced disease at presentation." (PMID 20130818, 2010). "The intimate association between the EGFR overexpression and cancer development has served as a platform for the introduction of newer therapies targeting these receptors." (PMID 21063399, 2010). "Activating KRAS mutations are important for cancer initiation and progression; and have recently been shown to cause primary resistance to therapies targeting the epidermal growth factor receptor." (PMID 21073737, 2010). "Adding EGFR staining increased the sensitivity of identifying ER- cancers with loss of wt BRCA1 (28/28; 100%), however it lowered the specificity as three of four of the ER- cancers without loss of wt BRCA1 (75%) stained for EGFR." (PMID 21080930, 2010). "The aim of this study was to determine EGFR gene status in H and N cancer patients treated with gefitinib and to correlate mutational status with clinico-pathological data and response." (PMID 21274259, 2010). "Detectable EGFR expression was found in 18% of cancers and was associated with high grade, advanced stages, and high risk for prostate-specific antigen recurrence by univariate analysis (p < 0.0001, each)." (PMID 27713352, 2010).
cancer (continued). "Previous studies have suggested that high expression of EGFR is associated with resistance to cancer therapy, including radiation therapy." (PMID 20731837, 2010). "Epidermal growth factor receptor (EGFR) abnormalities have been associated with several types of human cancer." (PMID 20657425, 2010). "A number of other authors have reported on the presence of EGFR kinase domain mutations in H and N cancers." (PMID 21274259, 2010). "With the inclusion of 92 patients, the overall incidence of EGFR mutations indicates that at 4% (4/92) they are rare among cases of H and N cancer within the Greek population." (PMID 21274259, 2010). "EGFR over-expression is associated with variety of cancers and linked to poor prognosis and decreased survival." (PMID 27713328, 2010). "The advantage of directly targeting critical transcription factors is that it bypasses several intermediate signal transduction molecules in the EGFR downstream signaling pathways that are often aberrantly regulated by mutations in cancer cells." (PMID 21209911, 2010). "Very recently, another class of transporters, sodium/glucose cotransporters (SGLTs), was shown to be associated with the epidermal growth factor receptor (EGFR) in cancer cells." (PMID 20182531, 2010). "Changes in expression and aberrant activation, especially of EGFR and ErbB2, are associated with a variety of cancers." (PMID 20459599, 2010). "EGFR-mediated signaling has been implicated in a variety of human cancers and is a key regulator of the cell proliferation, migration, metastasis, angiogenesis, and antiapoptosis processes." (PMID 19835603, 2009). "We robustly detected cancer gene mutations that direct clinical use and predict resistance to existing agents such as tyrosine kinase inhibitors (e.g., EGFR and KRAS mutations)." (PMID 19924296, 2009). "Structural and functional studies of the ABL and EGFR kinase domains have recently suggested a common mechanism of activation by cancer-causing mutations." (PMID 19714203, 2009). "By interfering with vesicle-mediated trafficking of EGFR, motuporamines considerably reduce plasma membrane-associated EGFR, and consequently its ability to control cancer cell migration." (PMID 19144191, 2009). "The epidermal growth factor receptor (EGFR or HER1) has been demonstrated to be involved in malignant transformation and cancer progression and its over-expression in cancer tissues has been associated with a more aggressive phenotype and a worse survival." (PMID 22276018, 2009). "Mutations, deletions and overexpression resulting in constitutive activation of EGFR have long been associated with various types of cancer." (PMID 19804630, 2009). "This area contains several candidate genes including the Neu3 gene (Human plasma membrane-associated sialidase) which is upregulated in several human cancers and is known to interact with EGFR." (PMID 19594952, 2009). "The most common mutation of the EGFR found in human cancer is EGFRvIII which has been found in more than 50 % of high and low grade gliomas and in 21 of 27 breast carcinomas, amongst others." (PMID 19804630, 2009). "In conclusion, mTOR inhibition causes antitumour activity in EGFR-resistant cancer cell lines and xenografts, and this effect seems to be mediated by inhibition of survival signalling pathways and angiogenesis." (PMID 18319715, 2008). "For several types of cancer, certain (secondary) mutations in the EGFR kinase domain have been reported that confer resistance to TKI." (PMID 18702090, 2008). "EGFR overexpression and/or hyperactivation is associated with a number of cancers such as breast, ovary, renal, non-small cell lung, head and neck, colorectal, pancreatic, prostate, cervical and bladder." (PMID 21892266, 2008). "These cancers and the patients in whom they occur have the same phenotype as the cancers in which EGFR mutations are found." (PMID 18182111, 2008).